HMGB3 (high mobility group box 3)
Diseases named in the same sentence as HMGB3 in open-access papers (continued):
Sharing a sentence is not in itself a finding about the gene and the disease.
ovarian carcinoma (continued). "The results showed that HMGB3 knockdown significantly impairs the spheroid forming ability of ovarian cancer cells and inhibits SOX2 and ALDH1A1 expression." (PMID 37328851, 2023). "Data from The Cancer Genome Atlas (TCGA) showed that HMGB3 was aberrantly expressed in a broad range of human cancer tissues, including ovarian cancer." (PMID 35332131, 2022). "IHC staining for HMGB3, cleaved caspase 3, and γH2AX verified that HMGB3 knockdown promoted cell apoptosis and the DNA damage response in ovarian cancer with olaparib treatment." (PMID 35332131, 2022). "A recent study demonstrated that the targeted depletion of HMGB3 sensitizes chemoresistant ovarian cancer cells to cisplatin through the inhibition of the ATR/CHK1/p-CHK1 DNA damage signaling pathway." (PMID 35332131, 2022). "The overexpression of HMGB3 increased the insensitivity of ovarian cancer to PARPi, whereas HMGB3 knockdown reduced PARPi resistance." (PMID 35332131, 2022). "have also showed that HMGB3 is upregulated in ovarian cancer cells, and its depletion promotes apoptosis of ovarian cancer cells." (PMID 35912216, 2022). "Our results suggested that HMGB3 possessed the potential to serve as a novel biomarker for tumor development and drug resistance in ovarian cancer." (PMID 35332131, 2022). "In the current study, we reported for the first time that HMGB3 promoted PARPi resistance in both BRCA1-deficient and wild-type ovarian cancer cells." (PMID 35332131, 2022). "HMGB3 knockdown dramatically increased the sensitivity of ovarian cancer cells to PARPi, whereas HMGB3 overexpression facilitated the resistance of ovarian cancer cells to PARPi." (PMID 35332131, 2022). "Several sequencing results from different research groups have demonstrated that HMGB3 is overexpressed in ovarian cancer tissues compared with control tissues." (PMID 35332131, 2022). "Paradoxically, HMGB3 high expression was shown to facilitate cisplatin resistance of ovarian cancer cells; however, we found it a favorable prognostic indicator of OV." (PMID 34777483, 2021). "Inhibition of HMGB3 in cisplatin-resistant ovarian cancer cells resulted in transcriptional downregulation of ATR and CHK1, subsequently attenuating the ATR/CHK1/p-CHK1 DNA damage signalling pathway." (PMID 33187536, 2020). "Here, we provide evidence for a role of HMGB3 in DNA damage processing and uncover new evidence for how HMGB3 may be contributing to cisplatin resistance in ovarian cancer cells." (PMID 41009989, 2025). "Therefore, the role of HMGB3 in cisplatin-induced DNA damage repair was investigated in these ovarian cancer cells." (PMID 41009989, 2025). "HMGB3 enhances the stemness, proliferation, and metastasis of ovarian cancer cells." (PMID 39062899, 2024). "HMGB3 promotes ovarian cancer resistance to PARP inhibitors through direct interaction with PARP1." (PMID 39062899, 2024). "Therefore, our results suggest that HMGB3 facilitates stem-like characteristics in ovarian cancer cells through activating MAPK/ERK signaling." (PMID 37328851, 2023). "As high HMGB3 expression is associated with lymph node metastasis in patients with HGSOC, we hypothesized that HMGB3 plays a role in ovarian cancer cell migration and invasion." (PMID 37328851, 2023). "Since RNA-seq indicated that HMGB3 mediates stem cell pluripotency and MAPK signaling, we investigated whether HMGB3 plays a role in maintaining ovarian cancer cell stemness." (PMID 37328851, 2023). "Hence, HMGB3 promotes ovarian cancer malignant phenotypes through activating the MAPK/ERK signaling pathway." (PMID 37328851, 2023). "Our data demonstrated that HMGB3 overexpression promotes ovarian cancer proliferation, migration, invasion, and stemness, which could be inhibited by HMGB3 knockdown." (PMID 37328851, 2023). "Targeting HMGB3 is a promising strategy for ovarian cancer treatment that may improve the prognosis of women with this disease." (PMID 37328851, 2023).
ovarian carcinoma (continued). "We found that HMGB3 enhances ovarian cancer cell stemness, proliferation, and metastasis." (PMID 37328851, 2023). "Our previous report demonstrated that HMGB3 is highly expressed in patients with HGSOC and that high HMGB3 expression is positively correlated with shorter overall survival; however, the function of HMGB3 in ovarian cancer proliferation remains unclear." (PMID 37328851, 2023). "Mechanistically, HMGB3 facilitated the activation of MAPK/ERK signaling in ovarian cancer." (PMID 37328851, 2023). "In this study, we further investigated the function of HMGB3 in ovarian cancer." (PMID 37328851, 2023). "The MAPK/ERK signaling pathway is reported to positively regulate cancer stemness; therefore, we explored whether MAPK/ERK is involved in HMGB3-induced increased ovarian cancer cell stemness." (PMID 37328851, 2023). "In the current study, we demonstrated that HMGB3 also positively regulates ovarian cancer stemness." (PMID 37328851, 2023). "To investigate whether the MAPK/ERK signaling pathway is required for HMGB3-mediated proliferation and mobility of ovarian cancer, we used two specific MAPK signaling pathway inhibitors, AZD6244 and PD0325901, to suppress MAPK/ERK activity." (PMID 37328851, 2023). "Next, to confirm whether HMGB3 activates the MAPK signaling pathway in ovarian cancer, western blot was used to examine the phosphorylation levels of p-MEK1/2 and p-ERK1/2, which are key factors in the MAPK/ERK pathway." (PMID 37328851, 2023). "In addition, we aimed to illuminate the role played by HMGB3 in the PARPi resistance of ovarian cancer and to further elucidate the potential molecular mechanisms underlying PARPi resistance." (PMID 35332131, 2022). "In conclusion, HMGB3 promoted PARPi resistance via interacting with PARP1, and the targeted inhibition of HMGB3 might overcome PARPi resistance in ovarian cancer therapy." (PMID 35332131, 2022). "HMGB3 deletion has been demonstrated to increase the cell sensitivity to cisplatin via the attenuation of ATR/CHK1/p-CHK1 DNA damage signaling pathway activation in ovarian cancer, suggesting an important role for HMGB3 in ovarian cancer." (PMID 35332131, 2022). "Additionally, HMGB3 depletion is suggested to reduce the cisplatin resistance of ovarian cancer cells." (PMID 34988076, 2021). "However, we have identified a role for HMGB3 in resistance to cisplatin, a DNA-damaging chemotherapeutic agent, in human ovarian cancer cells, suggesting that HMGB3 might be involved in DNA damage repair." (PMID 41009989, 2025). "Thus, HMGB3 promotes drug resistance by regulating DNA damage response pathways in ovarian cancer." (PMID 39062899, 2024). "Thus, our data prove that HMGB3 activates the MAPK/ERK signaling pathway in ovarian cancer cells." (PMID 37328851, 2023). "Thus, MAPK signaling inhibition by targeting HMGB3 may serve as a novel strategy for ovarian cancer therapy." (PMID 37328851, 2023). "In the current study, our results demonstrated that HMGB3, a well-known oncogene, promotes the malignant progression of ovarian cancer through activating the MAPK signaling pathway in vitro and in vivo, which may inform the development of new targeted therapy strategies for ovarian cancer." (PMID 37328851, 2023). "Thus, our data suggest that HMGB3 promotes ovarian cancer cell proliferation." (PMID 37328851, 2023). "Thus, our findings indicate that HMGB3 effectively promotes ovarian cancer proliferation in vivo." (PMID 37328851, 2023). "However, the function of HMGB3 in the development of PARPi resistance in ovarian cancer remains unclear." (PMID 35332131, 2022). "Thus, the targeted deletion of HMGB3 might have a promising future in overcoming PARPi resistance during the clinical treatment of ovarian cancer." (PMID 35332131, 2022). "Previously, we found that HMGB3 facilitates transcription of the DNA damage response kinases, ATR and CHK1, in human ovarian cancer cells." (PMID 41009989, 2025).
ovarian carcinoma (continued). "Hence, MAPK/ERK signaling may contribute to HMGB3-induced malignant progression of ovarian cancer." (PMID 37328851, 2023). "Next, we investigated the effects of HMGB3 and MAPK/ERK signaling on ovarian cancer proliferation in a xenograft model." (PMID 37328851, 2023). "Further, MAPK/ERK signaling was also activated during this progress, implying that HMGB3 and MAPK/ERK have important roles in modulating stem-like properties of ovarian cancer cells." (PMID 37328851, 2023). "Moreover, the clinicopathological characteristic analysis found that HMGB3-High was associated with lymph node metastasis and platinum resistance in HGSOC patients, indicating that HMGB3 might play a vital role in the development of chemoresistance in ovarian cancer." (PMID 35332131, 2022). "In ovarian cancer, HMGB3 promotes tumor resistance to chemotherapy drugs by regulating DNA damage response pathways, and the MAPK/ERK signaling pathway also contributes to the HMGB3-mediated progression of ovarian cancer." (PMID 38529373, 2024). "Our data also showed that HMGB3 suppression reduces the expression of major downstream target genes of the MAPK/ERK signaling pathway, including ETS-1, CCND1, and c-Myc, which have key roles in ovarian cancer occurrence and development." (PMID 37328851, 2023). "Besides, the overexpression of HMGB3 significantly reduced the protein levels of cleaved caspase 3 and cleaved PARP1 following olaparib treatment, whereas ovarian cancer cells with HMGB3 knockdown showed increased levels of cleaved caspase 3 and cleaved PARP1." (PMID 35332131, 2022). "Moreover, HMGB3 overexpression failed to enhance the proliferation and metastasis abilities of ovarian cancer cells with ERK1/2 knocked down." (PMID 37328851, 2023). "In addition, HMGB3 facilitated the development of PARPi resistance by directly interacting with PARP1 in ovarian cancer cells, and the inhibition of HMGB3 combined with PARPi might have broad prospects in the clinical therapy of ovarian cancer." (PMID 35332131, 2022).
bladder cancer (9 papers, 2015 to 2024). "For example, GLS plays an important role in cell growth and energy metabolism during cancer stage progression, while HMGB3 promotes cell proliferation and migration and is associated with poor prognosis in urinary bladder cancer." (PMID 26179909, 2015). "In the case of bladder cancer, decreased expression of microRNA-532-5p activates the HMGB3/Wnt/β-catenin signaling pathway, leading to increased proliferation and invasion of tumor cells." (PMID 39062899, 2024). "Esophageal squamous cell carcinoma and bladder cancer patients with high HMGB3 expression have poor prognoses." (PMID 36620553, 2022). "Previous research demonstrated that HMGB3 overexpression is connected to a poor prognosis in bladder cancer and esophageal cancer." (PMID 36620553, 2022). "HMGB3 promotes cell proliferation in bladder cancer and interacts with TOP2A and TOP2B, two targets for some anticancer agents." (PMID 28212608, 2017). "Reduced expression of miR-532-5p may contribute to a high rate of expression of HMGB3 in bladder cancer." (PMID 39062899, 2024). "In cultured bladder cancer cells, knockdown of circRNA TATA-box binding protein associated factor 15 (circTAF15) leads to suppression of cancer cell growth through downregulation of HMGB3 via direct suppression of miR-502-5p." (PMID 39062899, 2024). "Furthermore, previous studies have shown that HMGB3 participated in some types of cancers progression, such as urinary bladder cancer, esophageal squamous cell cancer, gastric cancer, non-small cell lung cancer, breast cancer." (PMID 28678825, 2017). "Further, IF staining of tumor tissue arrays from 782 patients with breast, lung and bladder cancer revealed two distinct populations: CitH3+MPO+ and CitH3+HMGB3+." (PMID 36973439, 2023).
glioblastoma (9 papers, 2020 to 2025). The most malignant astrocytic tumor (WHO grade IV). "We found that HMGB3 and YBX1 were predicted to target 11 risk genes for glioblastoma, including RPL5 and IDH1, as shared target genes." (PMID 39363111, 2024). "Research has found that circPCMTD1 can act as a miR-224-5p sponge to promote the progression of glioma and promote the progression of glioblastoma by regulating the miR-628-5p/HMGB3 axis." (PMID 34454424, 2021). "HMGB3 was proved to promote the proliferation and invasion of glioblastoma cells as well." (PMID 32699528, 2020). "Additionally, HMGB3 was found to be upregulated in glioblastoma and promoted cell proliferation and metastasis." (PMID 32131767, 2020).
non-small cell lung carcinoma (9 papers, 2017 to 2024). A group of at least three distinct histological types of lung cancer, including non-small cell squamous cell carcinoma, adenocarcinoma, and large cell carcinoma. "Overexpressing HMGB3 counteracted the effects of miR-513b on proliferation, invasion, migration, and apoptosis in non-small cell lung cancer (NSCLC)." (PMID 36428613, 2022). "Similarly, miR-758 was reported to inhibit proliferation, migration, invasion of non-small cell lung cancer cells by negatively regulating HMGB3." (PMID 32131767, 2020). "In non-small-cell lung cancer, apoptosis of A549 and H292 cells was facilitated by tanshinone IIA through the circ_0020123/miR-1299/HMGB3 axis, which raised miR-1299 expression while decreased circ_0020123 and HMGB3 expression." (PMID 37964867, 2023).
esophageal cancer (8 papers, 2021 to 2025). A primary or metastatic malignant neoplasm involving the esophagus. "To further explore the functional role of HMGB3, we silenced HMGB3 expression in two esophageal cancer cell lines using siRNA and confirmed successful knockdown by PCR." (PMID 40496864, 2025). "Experimental results in cell lines revealed that HMGB3 expression was significantly higher in esophageal cancer cells compared to normal esophageal epithelial cells." (PMID 40496864, 2025). "Several studies have shown that HMGB3 is a direct target of miR-27b and miR-145-5p in breast, cervical, and esophageal cancer cells." (PMID 39062899, 2024). "HMGB3, regulated by miR-216a, promotes esophageal cancer cell growth through enhancing Wnt/β-catenin pathway activity." (PMID 37328851, 2023). "In addition, the high expression of HMGB3 is also an important prognostic indicator of low survival rate in patients with esophageal cancer." (PMID 33960364, 2021). "Functional assays revealed that HMGB3 knockdown markedly suppressed ESCC cell proliferation, invasion, and colony formation, supporting its oncogenic role in esophageal cancer progression." (PMID 40496864, 2025). "A prognostic model consisting of six gene products (HMGB3, ARHGAP11A, H1.4, LRIG1, PRR11, and COL4A1) is a reliable predictor of esophageal cancer." (PMID 39062899, 2024). "A GEO-based prognostic model consisting of six gene products (ARHGAP11A, H1.4, HMGB3, LRIG1, PRR11, and COL4A1) has been shown to be a reliable predictor of esophageal cancer." (PMID 39062899, 2024).
glioma (8 papers, 2021 to 2025). A benign or malignant brain and spinal cord tumor that arises from glial cells (astrocytes, oligodendrocytes, ependymal cells). "The MiR-195-5p/HMGB3 regulatory axis also plays an important role in glioma: miR-195-5p inhibits HMGB3 expression by directly targeting HMGB3." (PMID 39062899, 2024). "In another study, HMGB3 was shown to be enriched in glioma cell-secreted exosomes and confer the activation of NLRP3 inflammasome and pyroptosis in tumor-associated macrophages." (PMID 39062899, 2024). "CircMMP1 induced proliferation and motility and inhibited the apoptosis of glioma cells by harboring miR-433 to enhance HMGB3 level, thus posing circMMP1/miR-433/HMGB3 axis for glioma therapy." (PMID 34887381, 2021).
prostate carcinoma (8 papers, 2020 to 2024). A carcinoma that arises from epithelial cells of the prostate gland. "Co-overexpression of SOX9 and HMGB3 is associated with prostate cancer progression and poor prognosis." (PMID 39062899, 2024). "Knockout of the Sox2 leads to suppression of the activity of the miR-452-5p/HMGB3 signaling axis and can cause inactivation of the Wnt/β-catenin signaling pathway, which can effectively slow the growth and metastasis of prostate cancer cells." (PMID 39062899, 2024). "Compared with other genes in this group, the expression of HMGB3 in prostate cancer cells was most suppressed by the expression of miR-205-5p, which plays an important role in pathogenesis." (PMID 39062899, 2024). "SOX2-OT knockdown inhibits the growth of prostate cancer in vivo by regulating the miR-452-5p/HMGB3 axis." (PMID 34394184, 2021). "It has been proved that the regulation of HMGB3 by tumor suppressive miR-205-5p suppressed cancer cell aggressiveness and participated in prostate cancer progression." (PMID 32699528, 2020). "HMGB3 was found to be downregulated in prostate cancer cells when these cells were transfected with miR-205 as demonstrated by a luciferase reporter assay." (PMID 32854238, 2020). "According to The Cancer Genome Atlas (TCGA) database, High Mobility Group Box 3 (HMGB3) is a gene which is responsible for shorter prostate cancer free survival and involved in prostate cancer pathogenesis." (PMID 32854238, 2020). "The level of HMGB3 expression is considered a prognostic marker of the survival of patients with cancer, including esophageal, breast, NSCLC, and prostate cancers." (PMID 39062899, 2024). "In prostate cancer tissues and cells, the expression of long non-coding RNAs Sox2-OT (SOX2 Overlapping Transcript) and HMGB3 increases, while the expression of miR-452-5p decreases." (PMID 39062899, 2024).
gastric adenocarcinoma (5 papers, 2018 to 2024).
leukemia (5 papers, 2018 to 2024). A malignant (clonal) hematologic disorder, involving hematopoietic stem cells and characterized by the presence of primitive or atypical myeloid or lymphoid cells in the bone marrow and the blood. "HMGB3 deficiency results in increased self-renewal capacity of HSCs, which can lead to leukemia, with which HMGB3 is closely associated in terms of occurrence and development." (PMID 39062899, 2024). "HMGB3 is reported to regulate the proper balance between hematopoietic stem cell (HSC) self-renewal and differentiation, and HMGB3 deficiency results in enhanced self-renewal capabilities in HSCs, which can induce the occurrence of leukemia." (PMID 35332131, 2022). "This leukemia variant depends on Wnt-β-catenin; the negative β-catenin regulator Apc is decreased and at the same time this leukemia is also characterized by high expression of ITGB3 as well as β-catenin (Ctnnb1) and High mobility group box 3 (Hmgb3)." (PMID 29342970, 2018).